ALDOA (aldolase, fructose-bisphosphate A)
Diseases named in the same sentence as ALDOA in open-access papers (continued):
Sharing a sentence is not in itself a finding about the gene and the disease.
liver cancer (16 papers, 2021 to 2026). An epithelial or non-epithelial malignant neoplasm that arises from the liver. "MYB- and HIF1α-co-regulated direct target, KRT19, exhibits positive correlation with HIF1α under hypoxia, while another target, ALDOA is shown to support hypoxic survival of liver cancer cells." (PMID 40680814, 2025). "Aldolase A (ALDOA) K230/K322la weakens the binding to DEAD-box helicase 17 in liver cancer stem cells, and Ikzf1 K164la significantly decreases the binding to TH17 differentiation-related gene promoters." (PMID 40994548, 2025). "We next explored the consequences of ALDOA depletion in a well-established genetically engineered liver cancer mouse model." (PMID 39833612, 2025). "Knockdown of ALDOA in liver cancer inhibits cell growth under hypoxic conditions, leading to delayed tumor growth and inhibition of migration." (PMID 40901472, 2025). "ALDOA is a key enzyme in glycolysis and gluconeogenesis and an important driving gene for the hypoxic growth of liver cancer cells." (PMID 40646880, 2025). "For instance, ALDOA has been shown to promote liver cancer growth and metastasis by accelerating mRNA translation and subsequently enhancing overall protein biosynthesis." (PMID 40305883, 2025). "Targeted inhibition of p300 or ALDOA is a new strategy to reverse the stemness of liver cancer stem cells." (PMID 40984037, 2025). "Using functional genomic screening, we show here that liver cancer cells show a unique sensitivity toward aldolase A (ALDOA) depletion." (PMID 39833612, 2025). "Here we report that liver cancer cells show a unique sensitivity toward depletion of fructose-bisphosphate aldolase A (ALDOA) despite other enzymes of the glycolytic pathway being largely dispensable." (PMID 39833612, 2025). "The phosphorylation of ALDOA can enhance glucose metabolism in liver cancer cells, promoting their growth and tumor formation." (PMID 39765841, 2024). "Here, it is shown that ALDOA promotes liver cancer growth and metastasis by accelerating mRNA translation independent of its catalytic activity." (PMID 37431681, 2023). "Collectively, these findings uncover a previously unappreciated nonmetabolic function of ALDOA in modulating mRNA translation and highlight the potential of specifically targeting ALDOA as a prospective therapeutic strategy in liver cancer." (PMID 37431681, 2023). "Subsequently, we observed that knockout of these metabolic enzyme genes in liver cancer cells significantly reduced cell proliferation; notably, knockout of ALDOA resulted in the lowest cell proliferation score across 16 liver cancer cell lineages." (PMID 37431681, 2023). "ALDOA has been proven to be an important regulator of the growth and progression of liver cancer cells under hypoxic conditions." (PMID 35804089, 2022). "Phosphorylation of ALDOA can enhance the glucose metabolism of liver cancer cells, thereby promoting their growth and tumor formation." (PMID 35804089, 2022). "Key resistance pathways include: lactylated IGF2BP3 activating PCK2-NRF2 to counter lenvatinib-induced stress; ALDOA lactylation enhancing liver cancer stem cell self-renewal for chemoresistance; MOESIN lactylation in Regulatory T cells (Tregs) weakening anti-PD-1 efficacy." (PMID 41685085, 2026). "The hub gene in our analysis ACSL5, ALDOA, and HKDC1 are directly associated with liver cancer." (PMID 38648205, 2024). "And ALDOA is also related to the prognosis of liver cancer patients." (PMID 35804089, 2022). "Although the function of ALDOA in tumor progression has been intensively studied, the role and mechanism of ALDOA in liver cancer, especially in ICC, has not been studied yet." (PMID 33994862, 2021). "In hepatocellular carcinoma, ALDOA K230/K322 lactylation weakens its strong binding affinity with DEAD-box helicase 17, leading to their dissociation in the cytoplasm and promoting DEAD-box helicase 17 nuclear translocation and SOX2 upregulation, sustaining liver cancer stem cells properties." (PMID 40994548, 2025).
liver cancer (continued). "In conclusion, this study reveals a previously unknown nonenzymatic function of ALDOA in liver cancer growth and metastasis and establishes a direct link between metabolic genes and overall mRNA translational control in cancer." (PMID 37431681, 2023).
lung squamous cell carcinoma (14 papers, 2014 to 2025). "Our pan-cancer analysis revealed that ALDOA is significantly upregulated across multiple cancer types, including lung squamous cell carcinoma, liver hepatocellular carcinoma, bladder cancer, and ovarian cancer." (PMID 41239433, 2025). "This study comprehensively elucidates the oncogenic role and clinical relevance of Aldolase A (ALDOA) across multiple cancer types, with a particular focus on lung squamous cell carcinoma (LUSC)." (PMID 41239433, 2025). "The mRNA expression of ALDOA was upregulated in 14 cancer types, including lung adenocarcinoma and lung squamous cell carcinoma." (PMID 34925439, 2021). "ALDOA is highly expressed in lung squamous cell carcinoma (LSCC) and depletion of ALDOA in lung squamous carcinoma cells reduces cell motility capabilities." (PMID 35222014, 2021). "The results demonstrated that all cell lines except H157 displayed abundant expression of ALDOA, and the human lung squamous cell carcinoma cell line H520 presented particularly strong expression." (PMID 29764507, 2018). "Our previous study demonstrated that aldolase A (ALDOA) is overexpressed in clinical human lung squamous cell carcinoma and that ALDOA promotes epithelial–mesenchymal transition and tumorigenesis." (PMID 29764507, 2018). "Here, we reported that ALDOA is a highly expressed in lung squamous cell carcinoma (LSCC) and its expression level is correlated with LSCC metastasis, grades, differentiation status and poor prognosis." (PMID 24465716, 2014). "We previously reported that ALDOA is excessively expressed in clinical human lung squamous cell carcinoma compared with adjacent normal tissues and that knockdown of ALDOA impairs the invasion and migration capacities of the lung squamous cell carcinoma cell line H520." (PMID 29764507, 2018).
lung adenocarcinoma (11 papers, 2017 to 2024). A carcinoma that arises from the lung and is characterized by the presence of malignant glandular epithelial cells. "To determine the mutation characteristics of ALDOA and its correlation with survival in lung adenocarcinoma, we performed an analysis on c-BioPortal databases." (PMID 34925439, 2021). "In the current study, ROC curve analysis suggested that ALDOA can act as a prospective non-invasive diagnostic biomarker to differentiate lung adenocarcinoma tissues from adjacent normal tissues." (PMID 34925439, 2021). "We downloaded the mRNA expression and associated clinical data of ALDOA in lung adenocarcinoma from TCGA." (PMID 34925439, 2021). "In the present study, we conducted bioinformatics analyses on ALDOA in lung adenocarcinoma patients, including transcriptional expression and mutation analysis, survival analysis, functional enrichment analysis." (PMID 34925439, 2021). "ALDOA had a high mutation frequency of 10% in lung adenocarcinoma (TCGA, PanCancer Atlas)." (PMID 34925439, 2021). "Nonetheless, the link between ALDOA expression levels and both the prognostic outcomes and the extent of immune infiltration in lung adenocarcinoma remains unexplored." (PMID 38256214, 2024). "As an important glycolytic enzyme, ALDOA is a potential prognostic biomarker and therapeutic target of lung adenocarcinoma." (PMID 37684969, 2023). "In the case of lung adenocarcinoma, Lu and co-workers observed that upregulation of ALDOA correlates with tumour progression and poor survival." (PMID 37377864, 2023). "Our data indicate that ALDOA expression level in lung adenocarcinoma, liver hepatocellular carcinoma, head and neck squamous cell carcinoma is higher than that in normal tissues." (PMID 35804089, 2022). "On the contrary, high levels of ALDOA were correlated with the poor prognosis of lung adenocarcinoma patients." (PMID 34925439, 2021). "To determine the potential relationship between ALDOA expression and immune infiltration levels in lung adenocarcinoma, we conducted a series of analyses by using TIMER." (PMID 34925439, 2021). "To further evaluate the relationship between ALDOA and tumor-infiltrating immune cells, we next explored the correlation between ALDOA expression and immunological markers in lung adenocarcinoma using the TIMER database." (PMID 34925439, 2021). "We also assessed the correlation between ALDOA and these markers in lung adenocarcinoma using the GEPIA2 database, and the results were similar to those in TIMER." (PMID 34925439, 2021). "The transcription level of ALDOA was upregulated in lung adenocarcinoma tissues than in normal tissues." (PMID 34925439, 2021). "Our data on survival analysis with GEPIA2 and the Kaplan Meier plotter indicated that lung adenocarcinoma patients with high ALDOA expression or genetic alteration have a poor overall survival prognosis." (PMID 34925439, 2021). "The GEPIA2 server indicated that the overall survival rate of lung adenocarcinoma patients with high ALDOA expression was significantly lower than that of patients with low ALDOA expression (p = 0.00021)." (PMID 34925439, 2021). "Univariate and multivariate analysis revealed that ALDOA is an independent poor prognostic factor for overall survival in lung adenocarcinoma." (PMID 34925439, 2021). "Consistent with the results of UALCAN, HPA showed protein expression of ALDOA in lung adenocarcinoma tissue was higher than that in normal lung tissue." (PMID 34925439, 2021). "In this study, based on the data from Oncomine, TCGA, UALCAN, and HPA, we revealed that the mRNA and protein expression of ALDOA is upregulated in lung adenocarcinoma tissues." (PMID 34925439, 2021). "Based on our data, we conclude for the first time that ALDOA is correlated with immune infiltration in lung adenocarcinoma." (PMID 34925439, 2021). "To evaluate the transcription level of ALDOA in multiple lung adenocarcinoma studies, we performed an analysis on Oncomine." (PMID 34925439, 2021).
lung adenocarcinoma (continued). "In this study, we explored the prognostic value and correlation with immune infiltration of ALDOA in lung adenocarcinoma." (PMID 34925439, 2021). "Our results link the expression of ALDOA with a poor prognosis and provide a potential therapeutic target for lung adenocarcinoma." (PMID 34925439, 2021). "ALDOA mRNA expression in lung adenocarcinoma patients was significantly increased with high T stage (p = 0.025), N stage (p = 0.013), M stage (p = 0.002), and TNM stage (p < 0.001)." (PMID 34925439, 2021). "Functional enrichment analysis was carried out to further explore the role of these positively co-expressed genes with ALDOA in lung adenocarcinoma." (PMID 34925439, 2021). "The result from UALCAN indicated that both mRNA and protein expression of ALDOA in lung adenocarcinoma tissues were significantly higher than that in normal tissues (p = 1.62E-12, p = 7.75E-31, respectively)." (PMID 34925439, 2021). "Consistently, the Kaplan Meier plotter showed that lung adenocarcinoma patients with high ALDOA were correlated with short overall survival (41.0 vs 55.1 months, p = 0.0022) compared to low ALDOA mRNA expression." (PMID 34925439, 2021). "In conclusion, our research suggests that the upregulation of ALDOA is correlated with tumorigenesis and metastasis in lung adenocarcinoma." (PMID 34925439, 2021). "All these results indicate that ALDOA is upregulated in lung adenocarcinoma tissues." (PMID 34925439, 2021). "Taken together, all these data suggest that these hub genes may play an important role in lung adenocarcinoma by cooperating with ALDOA." (PMID 34925439, 2021). "In this study, our results showed low levels of B cells, CD4+ T cells, macrophages, neutrophils, and dendritic cells were associated with poor prognosis of lung adenocarcinoma patients, while high ALDOA expression was correlated with poor prognosis in lung adenocarcinoma patients." (PMID 34925439, 2021). "We further speculate that ALDOA can regulate the expression level of tumor-infiltrating immune cells to affect the clinical prognosis of lung adenocarcinoma patients." (PMID 34925439, 2021). "The major strength of this study is our findings raise the possibility that the upregulation of ALDOA could be a potential prognostic marker in lung adenocarcinoma." (PMID 34925439, 2021). "ALDOA may regulate tumor-infiltrating immune cells to affect the clinical prognosis of lung adenocarcinoma patients." (PMID 34925439, 2021). "Moreover, a nomogram was constructed to predict the 1-, 3-, and 5-years survival probability of lung adenocarcinoma patients by combining the mRNA expression of ALDOA and clinical characteristics." (PMID 34925439, 2021). "Based on our results, we speculate that ALDOA may be involved in the progress of invasion and metastasis in lung adenocarcinoma." (PMID 34925439, 2021). "Our data reveal that ALDOA is an independent poor prognostic factor for lung adenocarcinoma." (PMID 34925439, 2021). "Given that there are significant differences between lung adenocarcinoma and normal tissues grouped by T stage, N stage, M stage, and TNM stage, we conclude that ALDOA might promote tumorigenesis and metastasis in lung adenocarcinoma." (PMID 34925439, 2021). "Taken together, these results suggest that ALDOA may regulate the expression level of tumor-infiltrating immune cells to affect lung adenocarcinoma and clinical prognosis." (PMID 34925439, 2021). "In addition, overexpression of AC122108.1 lncRNA promotes BM in lung adenocarcinoma through the Wnt/β-catenin pathway by directly binding to the aldolase A (ALDOA) protein; this mechanism enhances the proliferation, apoptosis, invasiveness, migration, and metastasis of lung adenocarcinoma cells." (PMID 36765679, 2023).
lung adenocarcinoma (continued). "The Cytoscape with cytoHubba tool kits, GEPIA, and c-BioPortal analysis suggested that upregulated hub genes of MRPL22, MRPL28, MRPL21, MRPL12, MRPS12, and MRPL17 are correlated with poor overall survival and may play a key role by cooperating with ALDOA in lung adenocarcinoma." (PMID 34925439, 2021). "As a result of their pancancer pattern, the relationship between ALDOA and FBP1 in patient prognosis is reversed, particularly in lung adenocarcinoma (LUAD) and liver hepatocellular carcinoma (LIHC)." (PMID 35404841, 2022). "In the present study, we reported that ALDOA copy number alterations were correlated with immune infiltration levels of B cells, CD8+ T cells, and CD4+ T cells in lung adenocarcinoma by TIMER." (PMID 34925439, 2021). "We also confirmed that ALDOA gene expression was inversely correlated with infiltrating levels of B cells, CD8+ T cells, CD4+ T cells, and macrophages in lung adenocarcinoma." (PMID 34925439, 2021). "However, ALDOA expression was negatively correlated with infiltrating levels of B cells, CD8+ T cells, CD4+ T cells, and macrophages in lung adenocarcinoma." (PMID 34925439, 2021). "However, the relationship between the expression level of ALDOA and prognostic value and immune infiltration of lung adenocarcinoma has not been studied." (PMID 34925439, 2021). "However, the role of ALDOA in lung adenocarcinoma has not been fully elucidated." (PMID 34925439, 2021).
gastric cancer (10 papers, 2014 to 2025). A primary or metastatic malignant neoplasm involving the stomach. "In this study, ALDOA has been identified as a promising diagnostic and prognostic marker for gastric cancer (GC) patients, although the underlying mechanisms are yet to be fully understood." (PMID 41049005, 2025). "Following univariate analysis, RBBP6, DCTPP1, HSPA4, and ALDOA expression levels were significantly associated with poor prognosis in 300 gastric cancer patients." (PMID 25379943, 2014). "As observed in this study, ALDOA was concluded to be significantly associated with the malignant potential of gastric cancer with regards to invasion depth, LN metastasis, and clinical stage." (PMID 25379943, 2014). "RBBP6, DCTPP1, HSPA4, and ALDOA expression in particular were significantly associated with a poor prognosis in the 300 gastric cancer patients." (PMID 25379943, 2014). "In gastric cancer (GC), several key enzymes and transporters, namely ALDOA, GLUTs, LDHA, and PKM2, have been widely investigated as potential biomarkers." (PMID 41154605, 2025). "Despite the valuable insights this study provides regarding the prognostic significance and association between ALDOA and ENO1 in gastric cancer, it has several limitations." (PMID 41049005, 2025). "The long-chain non-coding RNA PSMA3-AS1 functions as a competitive endogenous RNA and promotes gastric cancer progression by regulating the miR-329-3p/ALDOA axis." (PMID 40652273, 2025). "This study aimed to explore the clinicopathological significance and potential role of glycolytic enzyme aldolase A (ALDOA) in the carcinogenesis and progression of gastric cancer (GC)." (PMID 29992789, 2018). "However, changes in ALDOA expression in gastric cancer (GC) and their impact on tumor cells have been scarcely investigated." (PMID 41049005, 2025). "Clinically, elevated ALDOA expression correlates with deeper tumour invasion, lymph node metastasis, and advanced clinical stages, while proteomic analysis suggests that ALDOA may be associated with gastric cancer stem cells (CSCs)." (PMID 41154605, 2025). "In gastric cancer, lncRNA PSMA3-AS1 represses miRNA-329-3p, leading to increased ALDOA level, while knockdown of miRNA-329-3p or overexpression of ALDOA can partially attenuate tumor-suppressive effect of PSMA3-AS1 knockdown." (PMID 41361062, 2025). "Due to the unusually high expression of ALDOA and ENO1 in gastric cancer (GC) tissues, we sought to differentiate GC tissues from normal tissues based on their expression levels." (PMID 41049005, 2025). "The transition of malignant tissues into over-expressing ALDOA at the expense of the prevalent Aldolase isozyme in the normal tissue was also reported, along with the decrease of serum ALDOB levels in malignant tissues, including in patients with gastric cancer." (PMID 24993527, 2014).